RN7SL372P (RNA, 7SL, cytoplasmic 372, pseudogene)
Gene: Miscellaneous RNA gene on chromosome 1 (153,704,088 to 153,704,385, forward strand). Ensembl gene ENSG00000242565.
Homologues: Orthologues: chimpanzee Metazoa_SRP (98% identical), macaque Metazoa_SRP (93% identical). Paralogues in human: RN7SL1 (79% identical), RN7SL2 (79% identical), RN7SL3 (79% identical), RN7SL88P (77% identical), RN7SL296P (77% identical), RN7SL664P (77% identical), RN7SL814P (76% identical), RN7SL126P (76% identical), RN7SL322P (76% identical), RN7SL397P (76% identical), RN7SL492P (76% identical), RN7SL597P (76% identical), and 702 more.